NPHP1 (nephrocystin 1)
Diseases named in the same sentence as NPHP1 in open-access papers (continued):
Sharing a sentence is not in itself a finding about the gene and the disease.
Adult onset (1 paper, 2019). Onset of disease manifestations in adulthood, defined here as at the age of 16 years or later. "Moreover, in a recently published analysis from the iGeneTrain consortium, it was found that 0.5% of patients with adult-onset ESRD had a full gene deletion of the NPHP1 gene." (PMID 31921302, 2019).
glomerulosclerosis (1 paper, 2025). A hardening of the kidney glomerulus caused by scarring of the blood vessels. "At present, there are no reports about NPHP1 acting on glomeruli, but improved glomerulosclerosis has been observed in Nphp1del2-20/del knockout mice with re-expression of Nephrocystin-1." (PMID 41399018, 2025).
hydatidiform mole (1 paper, 2015). A gestational trophoblastic disorder characterized by marked enlargement of the chorionic villi, hyperplasia of the villous trophoblastic cells and hydropic changes. "In the DNA from CHM (complete hydatidiform mole, CHM1h-TERT), the OM consensus map showed an allele with the loss of the 45PROX but without the NPHP1 inversion, presenting a potential novel SV haplotype (termed H5)." (PMID 26641089, 2015).
late-onset nephronophthisis (1 paper, 2025). "NPHP1 is the most frequently involved gene in isolated late-onset nephronophthisis." (PMID 40102251, 2025).
Onset (1 paper, 2025). The age group in which disease manifestations appear. "In contrast to NPHP1-associated kidney disease, which may similarly account for adult-onset KF (PMID: 29654215), retinal impairment was not part of the phenotypic spectrum in any of the published cases with MAPKBP1 deficiency." (PMID 40814602, 2025).
Polydipsia (1 paper, 2018). Excessive thirst manifested by excessive fluid intake. "Patients with NPHP1 mutations had higher reported frequencies of polyuria (9/10; 90%), polydipsia (8/10; 80%), and enuresis (3/8; 38%) compared to all patients." (PMID 29974258, 2018).
kidney disease (12 papers, 2016 to 2025). "NPHP1 mutations cause familial juvenile nephronophthisis type 1 (NPHP1, OMIM 256100), another autosomal recessive renal disease that usually occurs years after birth." (PMID 27004562, 2016). "The five genes COL4A5, COQ8B, NPHP1, PAX2, and WT1 accounted for 66.9% of the monogenetic kidney disease diagnoses." (PMID 39363361, 2024). "Patients with JS with renal disease (JS-R) exhibit the features of a kidney disorder that is predominantly juvenile nephronophthisis (NPH), without defects in the retina; mutations of NPHP1 and RPGRIP1L are associated with this phenotype." (PMID 30518138, 2018).
retinopathy (4 papers, 2014 to 2024). "Our study also suggests that additional mutations in other NPHP genes may influence the penetrance of retinopathy in human NPHP1 patients." (PMID 33961633, 2021). "Our study suggests that additional mutations in other ciliary gate-related genes may affect the penetrance of retinopathy in human NPHP1 patients." (PMID 33961633, 2021). "We obtained retinal tissue samples from four retinopathy affected SVs and two control dogs and used them to quantitate transcript levels of the four retinal candidate genes, MERTK, NPHP1, ANAPC1 and KRCC1 in the critical region." (PMID 25517981, 2014).
cancer (3 papers, 2019 to 2024). A tumor composed of atypical neoplastic, often pleomorphic cells that invade other tissues. "Extreme NPHP1 gene scores, often underpinned by clear recessive inheritance, were observed in patients from diverse recruitment categories, including cancer, suggesting the possibility of a more widespread disease than previously appreciated." (PMID 37296294, 2023). "We were also able to confirm that the carrier frequency of NPHP1 heterozygous deletions was 0.35% within a non-rare-disease cohort (the GE100kGP cancer cohort) and 0.54% within the 1000 Genomes project." (PMID 39669628, 2024).
NPHP1 also shares sentences with these, for which no sentence is quoted: renal failure (4 papers); Juvenile nephronophthisis (3); autism (2); diabetes (2); Atrophy (1); autosomal-dominant tubulointerstitial kidney disease (1); basal cell nevus syndrome (1); blepharocheilodontic syndrome (1); brain malformations (1); collagenopathies (1); congenital heart disease (1); deafness (1); Denys-Drash syndrome (1); Duchenne muscular dystrophy (1); Floating-Harbor syndrome (1); fungal infection (1); genetic disorder (1); homocysteinemia (1); incontinentia pigmenti (1); Intellectual disability (1); language delay (1); Lowe syndrome (1); male infertility (1); Methylmalonic aciduria (1); neurodevelopmental disorder (1); neurological disease (1); partial epilepsy (1); Polyuria (1); psychiatric disorder (1); renal dysplasia (1).
A further 4 diseases each share a sentence with NPHP1 in 1 paper.